GZMB (granzyme B)
Diseases named in the same sentence as GZMB in open-access papers (continued):
Sharing a sentence is not in itself a finding about the gene and the disease.
tumor (continued). "To further investigate whether tumor uptake values of 68Ga-grazytracer PET can indeed reflect granzyme B levels in vivo, we performed PET imaging of 68Ga-grazytracer in 16 tumor-bearing mice." (PMID 35788116, 2022). "Moreover, owing to the heterogeneous spatial distribution of granzyme B in the tumor, differential immunofluorescence staining of granzyme B in serial slices was observed." (PMID 35788116, 2022). "This suggests that DBP and E2F8 in Th9 cells may function through regulation of Granzyme B for their anti-tumor function." (PMID 36241625, 2022). "Specifically, Granzyme A released from cytotoxic lymphocytes cleaves Gasdermin B (GSDMB) to trigger pyroptosis in target tumor cells, while cytotoxic lymphocytes secreted Granzyme B or chemotherapy-induced activated caspase 3 cleaves Gasdermin E (GSDME) to trigger tumor pyroptosis." (PMID 36280674, 2022). "Immunohistochemical analysis for the expression of PD-1 and granzyme B by tumours obtained from mice across the different treatments showed that muPD1-IL2v induced a significantly higher number of PD-1+ and granzyme B+ tumour-infiltrating lymphocytes (TILs) than the other treatments." (PMID 36171284, 2022). "In view of the remarkable effect of hPRDX5 on the proportion of NK cells in tumor tissues, we decided to further detect the expression of function proteins (such as IFN-γ, granzyme B, and perforin) of NK cells in tumor tissues of tumor-bearing mice in the treatment group and the control group." (PMID 36102418, 2022). "In addition, autophagy selectively destroys the NK-derived granzyme B in cancer cells, reducing tumor cell sensitivity to natural killer-mediated lysis." (PMID 36300110, 2022). "Although accumulation of MAIT cells with Th1 phenotype is seen in CRC tumor sites concomitant with expression of granzyme B, a protein pertinent to cytotoxic activity, whether these MAIT cells exert pro- or anti-tumor function remains obscure." (PMID 36551916, 2022). "Ex vivo immunofluorescence staining confirmed the comparably low granzyme B secretion on day 0 in the 2 tumor models; however, considerably higher granzyme B secretion was observed in the MC38 compared with the 4T1 tumors on day 6, which was consistent with the 68Ga-grazytracer PET imaging results." (PMID 35788116, 2022). "Macrophages are one of the components of tumor microenvironment known to contribute to creating an immunosuppressive microenvironment, which inhibits the activity of cells expressing granzyme B against tumor cells, even when tumor cells are infected with Epstein–Barr virus (EBV)." (PMID 35327381, 2022). "Third, 68Ga-grazytracer PET could also be expanded to monitor tumor responses to other immunotherapies related to granzyme B secretion, such as chimeric antigen receptor–T (CAR-T) and CAR-NK cell therapies." (PMID 35788116, 2022). "Moreover, hypoxia-induced autophagy degrades NK-derived Granzyme B in tumor cells through the autophagy sensor Inositol 1,4,5-Trisphosphate Receptor Type 1 (ITPR1), thus impairing NK-mediated tumor cell degradation." (PMID 35211123, 2022). "Interestingly, GZMB appears to be a pro-oncogene in our study, as it was upregulated threefold in tumor tissue." (PMID 35574296, 2022). "Histopathological analysis indicated that the tumor shrinkage induced by the trametinib/αPD-1 combination was associated with a massive infiltration and accumulation of activated CD8+ T cells, as determined by granzyme B and CD8 staining." (PMID 35292516, 2022). "Understanding the correlation with FoxP3 and GzmB under different tumor conditions may prove to be important in the generation of tumor targeting therapies." (PMID 35326588, 2022). "The different cytotoxic compounds may subsequently contribute to the eradication of tumor cells, as different components isolated from neutrophil granules, including MPO, defensins, granzyme B and NE, were able to kill tumor cells." (PMID 35884427, 2022).
tumor (continued). "Furthermore, western blot analysis showed increased levels of GZMB in DCZ0415‐treated tumours, validating our initial observation that TRIP13 inhibition increases levels of GZMB, indicating increased T‐cell infiltration." (PMID 35194944, 2022). "Interestingly, a recent study in a mouse model has shown that tumor-specific Tfh-B cells interactions as well as IL-21 production result in antitumor immunity by enhancing granzyme B expression by tumor-infiltrating CD8+ T cells." (PMID 35008422, 2022). "These included key genes associated with cytotoxic anti-tumor T cell responses (GZMA, GZMB, PRF1), co-stimulation of T cells (CD27, CD28, ICOS), and genes associated with other immune processes, including Type I IFN response (TNF, TNFSF10), as well as T cell exhaustion (CTLA4)." (PMID 36698398, 2022). "• More oligoclonal compared to SP or DN CD8+ TILs.• Recognize and kill higher proportion of autologous tumor cells.• Higher frequency of granzyme B、4-1BB、Ki-67-positive cells.• PMA-responsive genes and mitochondrial genes Keep stable.• Polyfunctional T Cells that can Produce IL-21 and GM-CSF." (PMID 36451828, 2022). "Given the fact that NK cells, as an important component of innate immunity, can also kill tumor cells via granzyme B secretion, we performed an in vivo depletion study to verify the contribution of granzyme B secreted by NK cells and CD8+ CTLs during immunotherapy." (PMID 35788116, 2022). "In addition, the tumor-restricted clonotypes expressed lower effector markers (GZMB, PRF1, IFNG) compared with clonotypes shared with other tissues, indicating possible antigen-experience and exhaustion of TCR clonotypes in the TME." (PMID 36185254, 2022). "Tc cells secrete pro-inflammatory cytokines TNF and IFN-γ that have cytotoxic effects on tumor cells, further, Tc cells can directly kill cells through secretion of perforin and granzyme B that generate pores in the plasma membrane and activate cellular caspases, respectively." (PMID 36072595, 2022). "Moreover, VNP-GD/EI-NP@Gel+aPD-1 also potently increased the number of activated Granzyme B+ CD8+ T cells in the tumor, which was significantly higher than that in the VNP-GD@Gel and VNP-GD/EI-NP@Gel groups." (PMID 36280674, 2022). "Moreover, the expression levels of CD8, IFN-γ and Granzyme B in tumor tissues were overall increased after SPIN injection and US irradiation compared to those in the control group." (PMID 35821238, 2022). "Tumors from SV.IgGOX40-treated mice showed significant cell lysis and the presence of CD8 T cells and granzyme B. It is likely that greater amounts of αOX40 could be delivered to the tumor by SV infection that can also produce a proinflammatory response." (PMID 36611875, 2022). "Moreover, ATO potentiated anti-PD-L1 antibody therapy in syngeneic tumor models, which correlated with enhanced granzyme B secretion from cytotoxic T cells." (PMID 36015287, 2022). "The trafficking levels of CD8 and CTLs represented by granzyme B in tumor slices were traced." (PMID 36156442, 2022). "However, treatment with the PKM2 targeting compound TEPP-46 and PD-1 checkpoint blockade significantly increased the populations of GzmB+ and NKp46+ NK cells and decreased tumor cell survival compared with the TGF-β1-treated group." (PMID 34862460, 2022). "Accordingly, administration of IFNα-MSCs to mice bearing B16F0 cells could dramatically promote the expression of GZMB in tumor infiltrated CD8+ T cells." (PMID 35145233, 2022). "Switched memory B cells, that are found in both tumor and blood, displayed modest GZMB expression." (PMID 35392082, 2022). "Incubation of OVCAR3-FSHR target cells plus human PBMCs with D2AP11-TCE led to the significant induction of IFN-γ, soluble Fas (sFas), granzyme A, granzyme B, and perforin compared with empty vector control at 48 hours, and this construct drove robust tumor antigen-specific killing." (PMID 36509287, 2022). "Human and mouse basophils release granzyme B that exerts a cytotoxic effect on tumor cells." (PMID 36578500, 2022).
tumor (continued). "SCH58261 increased the expression of granzyme B in tumor-infiltrating CD8 + T cells." (PMID 36419058, 2022). "Importantly, knockdown of Dbp and E2f8 genes in CD4+ T cell suppresses and promotes Granzyme b, respectively, in Th9 cells in vitro and also in Granzyme B+ T cells in tumor-bearing mice in vivo." (PMID 36241625, 2022). "In addition to the tumor epithelium marker PanCK, Granzyme B which is required for cytotoxic action of CD8+ T cells is increased at significantly higher levels in tumor when compared to tumor-adjacent stroma (TAS)." (PMID 36230846, 2022). "Finally, we observed the presence of GZMB+ CD11b+ cells, often localized within CD31+ vasculature, indicating circulation of cytotoxic immune cells within non-tumor-associated dura." (PMID 35534852, 2022). "Additionally, the cell-killer granzyme B (GZMB) is released to tumor cells by cytotoxic lymphocytes, followed by cleavage of GSDME by GZMB, inducing tumor cell pyroptosis." (PMID 36189207, 2022). "Inflammatory proteases from neutrophils (proteinase 3, elastase, and cathepsin G) and mast cells within the tumor microenvironment (chymase, tryptase, and granzyme B) can process full-length IL-33 into shorter mature forms (18–21 kDa), with a 10- to 30-fold higher amount of activity." (PMID 35409061, 2022). "Tissue-resident memory T (TRM) cells are tumor antigen-reactive TILs that produce a magnitude of cytotoxic mediators, such as granzyme B and perforin, as well as cytokines, such as interferon-gamma (IFN-γ) and tumor necrosis factor (TNF), in the tumor microenvironment (TME)." (PMID 35663939, 2022). "Interestingly, our study suggested that GZMB acted as a tumor suppressor in BC, and its expression was significantly decreased in the high-risk group, which was consistent with previous results." (PMID 35464869, 2022). "It was therefore suggested that the presence of granzyme B+ tumour-infiltrating cells might be an independent prognostic factor in dogs affected with this malignancy." (PMID 35324835, 2022). "Further studies, perhaps through a modification of our adoptive T cell transfer experiment in tumor-bearing Rag-/- mice using CD4 T cells from perforin/GzmB knockout mice could provide further details on the exact mechanism." (PMID 36569934, 2022). "Perforin forms pores on tumor cell membrane and allows granzyme B to enter tumor cells." (PMID 35757715, 2022). "Therefore, a decoration of MNPs with granzyme B resulted not only in an efficient homing of NPs to tumor cells, but also provides therapeutic effects via the stimulation of a granzyme B-mediated apoptosis." (PMID 34905138, 2021). "In a mesothelioma model, pretreatment of tumors with cisplatin increased gene expression of IFNγ and granzyme B, which could be further increased by subsequent α-GalCer administration, resulting in increased tumor regression." (PMID 34680322, 2021). "pDCs secrete granzyme B to the extracellular area, where it plays dual roles for anti-tumor immunity as it would help process peptide antigen to facilitate cross-presentation while generally suppress T cell activation and expansion through degrading the zeta chain of its TCR." (PMID 33868318, 2021). "In addition, the expression of granzyme B in the tumor tissues was detected to examine the tumor killing effect by cytotoxic TILs." (PMID 34006860, 2021). "One of the documented shortcomings of the aldehyde granzyme B tracers is low tumour retention, which may be masked in tumours originating in tissues with higher nonspecific retention including liver and kidneys." (PMID 35936114, 2021). "We found Y111, but not CD3 Isotype or PD-L1 mAb could significantly enhance the secretions of IFNγ, TNFα, and granzyme B from the expanded Vγ2Vδ2 T cells in the presence of tumor cells." (PMID 34040604, 2021). "Down-regulation of granzyme B is a feature of intra-tumoral, as opposed to peri-tumoral, NK cells and correlates with expression of IL-10-positive tumour-associated macrophages." (PMID 33995362, 2021).
tumor (continued). "After being released, it can bind with its specific receptor, namely CCR8, on peripheral Tregs and attract them to tumor sites where it induces a STAT3-dependent elevation of granzyme B level that would confer Tregs with a powerful weapon against their targets." (PMID 33868318, 2021). "Further studies into the application of CD4+ GzmB+ T cells in tumor immunotherapy are needed." (PMID 34631551, 2021). "Cytotoxic CD8+ T cells generated Granzyme B (GzmB) to kill tumor cells." (PMID 34258151, 2021). "As a pro-apoptotic serine proteinase, granzyme B, which is primarily secreted by activated cytotoxic T cells and natural killer cells, plays a fundamental role in mediating the eradication of infected cells, allogenic cells, and tumor cells." (PMID 34944392, 2021). "Notably, tumor cells can adapt to hypoxia by activating autophagy, which has been shown to also target NK cell derived granzyme B and, thereby, protect tumor cells from NK cell mediated cytotoxicity." (PMID 33782423, 2021). "In addition, we found GZMB to be endogenously expressed in CMS2 tumor cells and to be prognostic in a T cell independent fashion." (PMID 34972191, 2021). "By contrast, NK cell recruitment and activation were associated with promoting anti-tumour effects following injection of an IL-12 expressing Maraba virus vaccine against peritoneal tumours with increased IFN-γ, and granzyme B production, NK mediated cytotoxicity and migration." (PMID 34888493, 2021). "Interestingly, granzyme B was found to be incorporated in tumor cells by explicitly binding to mHSP70, which results in perforin-independent apoptosis of the cells." (PMID 34572948, 2021). "Furthermore, the function of T cells was tested through flow cytometry, and we found that PRMT5 deficiency in tumor cells enhanced IFN-γ, TNF-α and granzyme B secretion by CD8+ T cells." (PMID 34522232, 2021). "Our results show that, while the immunomodulatory mode of action of the chemotherapies may be different, the ultimate mechanism of tumor lysis through release of Granzyme B is an accurate biomarker for treatment response." (PMID 33713000, 2021). "However, in agreement with our tumor model data, we observed that the frequency of Granzyme B+ OT-I was considerably lower in both the α4-1BB and isotype-control treated groups treated with high-dose EZH2i." (PMID 34925340, 2021). "A study has shown that the ureido-sulfonamide CAIX inhibitor SLC-0111 in combination with anti-PD-1 and anti-CTLA4 increased the effector function of T-cells (granzyme B production), inhibited tumour growth, and reduced metastasis in the B16.F10 and 4T1 syngeneic tumour models." (PMID 33923305, 2021). "In addition, CD68 (macrophage) is highly correlated to antigen-presentation responses (HLA-DRA, r = 0.71 and 0.60 in normal and tumor tissues, respectively) and moderately correlated to GZMB (r = 0.54 and 0.47 in normal and tumor tissues, respectively)." (PMID 34758832, 2021). "B cells expressing granzyme B have been postulated to possess antiviral and early tumor immunosurveillance functions, with granzyme B+ B cells exerting granzyme-mediated cytolytic activity against tumor cell lines in vitro." (PMID 33427210, 2021). "Furthermore, tumor-infiltrating Batf−/− CD8+ T cells had significantly lower expression of the cytolytic effector molecule granzyme B." (PMID 33809259, 2021). "In addition to Teffs, tumor-infiltrating CD8+ Trm T cells also exhibit anti-tumor activity by releasing lytic granules, granzyme B (GzmB), IFN-γ, and tumor necrosis factor (TNF)-α." (PMID 34742349, 2021). "Furthermore, we pre-selected tumor type and concentrations of Granzyme-B, TNFα, and IFN-γ on day seven for evaluation on model parameter Vmax5,2." (PMID 34205020, 2021). "Moreover, Y111 increased the cytotoxicity of the expanded Vγ2Vδ2 T cells against various NSCLC-derived tumor cell lines with the releases of granzyme B, IFNγ, and TNFα in vitro." (PMID 34040604, 2021).
tumor (continued). "In contrast, other classical markers of T-effector, NK and pDC cells were not expressed in cancer cell lines, supporting the hypothesis that GZMB is produced by tumor cells in CMS2 CRC tumors and primarily by immune cells in CMS1 CRC tumors." (PMID 34972191, 2021). "Furthermore, the density of CD4+ GzmB+ T cells in the central region of the tumor is an independent predictor of prognosis in pMMR CRC patients and can also predict the outcome of patients after neoadjuvant chemotherapy." (PMID 34631551, 2021). "Since cell-to-cell contact is not necessary to all GrB-mediated immunosuppressive processes, one may wonder if the secreted granzyme B would escape from its original mission and harm adjacent tumor cells instead." (PMID 33868318, 2021). "Furthermore, inhibition of ITPR1/autophagy in tumors significantly increases granzyme B activity and improves NK-mediated tumor extinction." (PMID 33422072, 2021). "Together, these results suggested that density of CD4+ GzmB+ T cells were central to tumor progression and survival, which could be considered as a potential target for immunotherapy." (PMID 34631551, 2021). "At the same time, the expression of Granzyme B and perforin in Tregs was decreased after RFA and cryo-thermal therapy compared to tumor-bearing mice; however, after cryo-thermal therapy, the levels of Granzyme B and perforin in Tregs were much lower than those in the RFA group." (PMID 34576115, 2021). "Importantly, tumor-bearing mice that received the combination treatment of compound 968 and anti-PD-L1 antibody had the highest granzyme B-producing cell fractions." (PMID 34944392, 2021). "During immune surveillance, cytotoxic T lymphocytes (CTLs) could be engulfed into the vacuoles of tumor cells where granzyme B was degranulated." (PMID 33868318, 2021). "CD19 is presently thought to be the best accessible target for CAR-T cell treatment in blood cancer, whereas autophagic degradation of GZMB represents a novel method for hypoxic tumor cells to avoid natural killer cell-mediated lysis, and IFNG is important in maintaining immune homeostasis." (PMID 34893051, 2021). "Granzyme B, a serine protease, has been shown to interact with membrane-bound Hsp70 on tumor cells." (PMID 34905138, 2021). "CircIGF2BP3 depletion alleviated tumor cell-mediated immune suppression, as determined by the expression of perforin, granzyme B (GzmB) and secreted IFN-γ and TNF-α from cocultured PBMCs, whereas circIGF2BP3 overexpression compromised the expression or secretion of these immune effectors." (PMID 34416901, 2021). "Nonetheless, the details of how CD4+ GzmB+ T cells located in the central tumor affects the anti-tumor immunity remains unclear and controversial, especially in pMMR CRC." (PMID 34631551, 2021). "In addition, increased expression of CD8α, CXCL9, CXCL10, Granzyme A (GZMA), Granzyme B (GZMB), and IFN-γ was observed in Six1-deficient tumor tissues." (PMID 34782761, 2021). "Following binding and uptake, granzyme B is able to efficiently kill mHsp70+ tumor cells." (PMID 34079819, 2021). "Activated CD8 T cells and NK cells release Granzyme B leading to apoptosis of the tumor cells." (PMID 33713000, 2021). "Helped CD8+ T cells then upregulate molecules such as granzyme A, granzyme B, perforin, fas ligand, trail, and IFNγ, which play roles in cytotoxic effector function, and may help delay distal tumor growth." (PMID 36405502, 2021). "In addition, transcription levels of the well-known cytolytic proteins granzyme B and perforin and pro-apoptotic proteins Bax, Bak, and cytochrome C were also increased in tumor tissues from Poly6-challenged mice." (PMID 33499256, 2021). "Moreover, the cytotoxicity assay also proved that blocking Ogr1 impelled T cells to migrate to the tumor’s boundary, and killed tumor cells by secreting sufficient granzyme B, TNF, and an appropriate amount of IFN-γ." (PMID 34158625, 2021).